CD69 (CD69 molecule)
Diseases named in the same sentence as CD69 in open-access papers (continued):
Sharing a sentence is not in itself a finding about the gene and the disease.
infection (continued). "Alternatively, since CD69 is a nonspecific marker of lymphocyte activation, an immune response to another infectious agent would have elevated a participant’s baseline CD69 level, making it difficult to determine whether their PBMCs were responding to coccidioidin or another infection or both." (PMID 25148473, 2014). "At this early time point of infection no significant activation of NK and NKT cells, indicated by the expression of CD69, was found (3B and data not shown)." (PMID 24182203, 2013). "Further indication of OT-I cell activation during infection is provided by the down-regulation of CD62L and up-regulation of CD44 and CD69 (not shown)." (PMID 21829561, 2011). "This high dose, which is equivalent to the dose present in the lung at the peak of infection with 105 CFU live bacteria, failed to induce CD69 expression on NK or T cells, in either the lungs or MdLN." (PMID 20585449, 2010). "Like CD69, the proportion of MAIT cells expressing the T cell proliferation marker CD71 was significantly higher during VZV infection compared to mock infection, although we did not observe an overall difference in the number of MAIT cells between mock and VZV infected cultures." (PMID 37006246, 2023). "Nine vaccine recipients without evidence of prior infection and paired samples showed significant increases in CD4+ T-cell activation by expression of CD69 and CD137 in response to spike peptide pool stimulation after subtraction of the unstimulated control (median difference, 0.04%; P = .04)." (PMID 38107018, 2023). "The specific EVs surface marker characterization (CD49e, CD209, CD69, CD142, and CD20) allowed for the drawing of a defined EV signature, useful to discriminate between patients negative for SARS-CoV-2 who experienced infection symptoms and those with positive clinical status of the infection." (PMID 37896755, 2023). "Striking was the biphasic increase in CD69 on CD8 T-cells, which was reminiscent of the double fever peak, and the acute peak in Ki67 expression on CD4 and CD8 T-cells that had not been observed upon pH1N1 infection." (PMID 33671829, 2021). "Similarly, higher proportions (>2×) of B cells from male mice were activated (CD69+) than those from female mice and further increased (~3×) in B cells of male mice after TMEV infection but not in B cells of female mice." (PMID 32727036, 2020). "Non-activated (CD25−, CD69−) CD4+ T cells were highly permissive to entry by X4-tropic HIV, with viral entry detected in 65% ± 11% of resting CD4+ T cells at the multiplicity of infection used (top)." (PMID 30943397, 2019). "Despite the lack of productive infection in the vast majority of NK cells, in vitro infection with IAV induced a marked increase in CD69 expression on CD56bright and CD56dim NK cells in both blood and lung, indicating that IAV infection of mononuclear cells activates NK cells." (PMID 31156653, 2019). "A study in immunocompetent mice showed that activated NK cells with upregulated CD69, IFN-γ, and perforin accumulated in the lungs in the early stage after aerosol infection with MTb, but depletion of NK cells did not influence the course of infection." (PMID 31293580, 2019). "However, we did not observe differences in absolute numbers of CD69+ TEM cells before and after infection (data not shown)." (PMID 26793197, 2015). "We have shown previously in mice, that infection with live viruses, including influenza/A and Semliki Forest virus (SFV), induces systemic partial activation of lymphocytes, characterized by cell surface expression of CD69 and CD86, but not CD25." (PMID 21998693, 2011). "Similarly, infection activated CD4+ T cells in BALB/cJ mice, as shown by the increased percentage of CD69+ CD4+ T cells, but it did not activate T cells in IgD deficient mice." (PMID 19859584, 2009).
infection (continued). "Importantly, TNFR1/2-/- mice not only had decreased numbers of activated CD69+ NK cells in the spleen and lungs at D8, but also decreased CD69+NK1.1int cells at D3, indicating impaired NK cell maturation and activation in the absence of TNF receptors at early stages of infection." (PMID 35479068, 2022). "However, for CD4+ cells generated in the absence of I-Ab molecules, a two-fold increase in CD69 expression was already observed in non-infected mice (compared to non-infected WT mice), which is a known feature of NKT cells, and infection led to additional augmentations of these values." (PMID 21814579, 2011).
cancer (112 papers, 2012 to 2026). A tumor composed of atypical neoplastic, often pleomorphic cells that invade other tissues. "Adaptation to the TME bears hallmarks of tissue-residency, including CD49a and CD69 expression, alongside the loss of the basic cNK effector functions of efficient cancer-cell killing and the recruitment and activation of DCs." (PMID 38267402, 2024). "In regard to other risk factors, CD69 is expressed in several hemopoietic cells, and it takes part in cancer immunity." (PMID 29158988, 2017). "High CD69 levels are associated with poor prognosis in cancer." (PMID 41597427, 2026). "CD69 upregulation by Jurkat cells expressing MC.27.759S or MC.7.G5 TCRs in response to 4 different cancer cells was enhanced by the presence of CD8-αα or CD8-αβ, with similar levels of CD69 seen for CD8-αα or CD8-αβ." (PMID 39744940, 2025). "The results show antigen-specific CD69 expression on TAC01-CLDN18.2 cells after incubation with CLDN18.2-positive cancer cells." (PMID 39404622, 2025). "CD69 has been identified as a biomarker that promotes the malignant progression of various cancers and is highly expressed in AML." (PMID 41164126, 2025). "In the AML cohort, CD69 expression was positively correlated with the immune microenvironment abundance of pro-cancer immune cells, including CD56dim natural killer cells, immature dendritic cells, and MDSCs." (PMID 41164126, 2025). "Ly108 and CD69, relevant for tissue residency, have been linked to T-cell exhaustion development in experimental models of chronic infection and cancer: TPEX cells (Ly108+CD69+) can transition via Ly108-CD69- to Ly108-CD69+ TEX." (PMID 40897819, 2025). "The MFI of the activation marker CD69 in CD19+ B lymphocytes was higher in cancer patients compared to volunteers (p = 0.002)." (PMID 40802351, 2025). "The results demonstrate that UniCAR T-cells are specifically activated and upregulate CD69 in the presence of GRPR-expressing cancer cells (PC3 or LNCaP) and the BBN2 TMs." (PMID 40141329, 2025). "Peripheral blood immunophenotyping showed significantly increased CD69+ and PD-1+ T cells in cancer patients (p < 0.01)." (PMID 38256645, 2024). "Increased CD69 expression suggested that transduced T cells are more responsive to the presence of cancer cells." (PMID 39450160, 2024). "In line with this, a study conducted on the Cancer Treatment Response gene signature DataBase revealed CD69 expression as a prognostic factor for responding to PD-1 blocking therapy." (PMID 37901220, 2023). "Based on this, individuals in the active TB group were enriched for CD4+ and CD8+ cells expressing CD69 compared with previous TB or cancer controls, reaching significance for CD8+ T cells." (PMID 33848273, 2021). "In murine cancer models, it was discovered that CD69 and CD103 on T cells act in a sequential nature, where CD69 is crucial for the entering of the tissue and CD103 for the persistence of the cell in the tissue." (PMID 33467084, 2021). "Upregulation of PD-L1 in cells having S339E increased cancer viability by defending the cells from the immune response of activated T lymphocytes, as determined by CD69 and CD25 expression." (PMID 33963314, 2021). "Liver-resident NK expresses CXCR6 and CD69 markers, which have crucial cytotoxic activity against cancer cells." (PMID 32235370, 2020). "In particular, cancer cells, such as Hep-3B, can release miR-92b-rich exosomes that exert a suppressive action on NK by deregulating CD69, which is a cell surface costimulatory molecule determining cell proliferation, cytokine secretion, and cytotoxicity." (PMID 32235370, 2020). "For example, both analysis methods identified the increased frequency of TEM phenotype CD44hi CD62Llo in cancer septic animals relative to previously healthy controls, as well as increased expression of markers of acute activation CD69 and CD25." (PMID 29338031, 2018). "We further found that overexpression of CD69 intensified the proapoptotic effect of ketamine on cancer cells." (PMID 29453833, 2018).
cancer (continued). "Paired comparison of the normal and cancer samples also indicated the downregulation of CD69 in the cancers." (PMID 29453833, 2018). "If an anti-CD69 antibody was used to inhibit CD69 expression, an antitumor effect was observed in cancer-bearing mice, suggesting the antitumor effect of the CD69 antibody." (PMID 25310154, 2014). "The cancer patients also exhibit an enhanced percentage of activated T cell subsets and NK cells, as determined by an increase in the density of CD69, CD71 and CD98." (PMID 23251433, 2012). "A correlation analysis of TCGA data from various cancers showed that CD69 expression correlated positively with immune checkpoint expression and immune infiltration, whereas SBK1 correlated positively or negatively with the same parameters, depending on the cancer type." (PMID 40989699, 2025). "Even without encoding immunogenic cytokines (SFV-GFP replicon particles), rSFV-infected cancer cells induced strong migration of PBMC through a transwell and caused upregulation of CD4 and CD8 T cell degranulation (CD107) and differentiation (CD69) markers in cancer cell monolayers." (PMID 38425844, 2024). "Interestingly, the co-culture of PBMCs with VSV-NDV-infected cancer cells mediated a significant upregulation of CD69 levels on human CD4+ and CD8+ T cells, while CD25 was additionally upregulated on CD8+ T cells." (PMID 39410025, 2024). "Notably, in 2019, genes such as CD69 and CXCL9 were identified; both are closely linked to immune responses and cancer prognosis, suggesting new directions for research." (PMID 38919494, 2024). "Similarly, Following JRT3-LES treatment with SCZ (5μM) for 24 hours in the presence of EPCR-expressing HT29 cancer cells also strongly upregulated CD69 expression." (PMID 38250065, 2023). "However, CD69 expression on memory CD8 T cells is required for cancer cell elimination and the maintenance of cancer-immune equilibrium." (PMID 36045683, 2022). "In addition to inflammation-related genes, this CD8 lymphocyte subcluster highly expressed HLADR isotype and CD69 which were previously reported to promote cancer apoptosis." (PMID 36148946, 2022). "We found that CD8+CD103+CD69+ T cells were present across different cancer stages." (PMID 32610077, 2020). "Activated CD8+CD69+ T cells can establish immunological memory and may kill cancer cells outside the illumination field." (PMID 31906092, 2019). "We found that CD69 was downregulated in the cancer tissues compared with normal tissues." (PMID 29453833, 2018). "CD69 was downregulated in LUAD patients’ cancer tissue compared with the normal tissue." (PMID 29453833, 2018). "CD69 mRNA was significantly higher in patients with UC and dysplasia than in UC or UC and cancer." (PMID 25595911, 2015). "Cancer antigens in the TCL could effectively activate immune cells that were characterized by an increase in the expression of CD69 on these cells." (PMID 25310154, 2014). "Indeed, upregulation of CD69 and OX-40 may enhance T cell activation and proliferation, both of which can be beneficial in cancer immunotherapy." (PMID 37239929, 2023). "Some of the significant cancer hallmark terms are inflammatory response (CD14, CD69, IL10RA), KRAS signaling up (CD37, IL10RA, GPNMB), IL-6/JAK/STAT3 signaling (CD14, CSF2RB), Interferon Gamma Response (CD69, CSF2RB, IL10RA, VCAM1, SLAMF7), TNF-alpha Signaling via NF-kB (CD69)." (PMID 35486660, 2022). "However, the differences werestatistically significant for NKG2D+cells betweenPBLs cultured alone and the same cells cultured withbreast cancer ASCs (P<0.05) and for CD69+cellsbetween unexposed PBLs versus those cultured withbreast cancer and normal ASCs (P<0.01 and <0.05,respectively)." (PMID 28367424, 2017). "The resulting activation can be measured by upregulation of CD69 and CD71 markers on the surface of the T cell, followed by a lysis of the cancer cell (right)." (PMID 41333282, 2026).
cancer (continued). "Lectibody-induced T cell activation resulted in a significant increase in CD69 and CD71 surface expression in PBMCs incubated with SadP-scFv UCHT1 and Gb3 positive cancer cells." (PMID 41333282, 2026). "Remarkably, we observed an increased proportion of CD8+ T cells expressing activation markers CD69, Granzyme B, and IFN-γ exclusively in the presence of T-DXd-treated cancer cells." (PMID 39449023, 2024). "A number of inhibitory immunoreceptors have been identified and studied in cancer in past decades, including but not limited to PD-1, PD-L1, CTLA-4, LAG3, HAVCR2, TIGIT, CD69 and CD40." (PMID 37989761, 2023). "Pre-treatment of CD8+ T cells with anti-CD11a antibodies (LFA-1 blockade), reduced CD69 and CD44 expressions on T cells after co-culture experiments, indicating that ICAM1 on cancer cells mediates the interaction with T cells by binding to LFA-1." (PMID 36871040, 2023). "The same phenotype has been observed in cancer: Nrp-1 expression on CD8+ T cells was accompanied by elevated expression of CD44, CD69 and CD25, but also by several co-inhibitory molecules such as PD-1, CTLA-4, Lag-3 and Tim-3." (PMID 38019895, 2023). "CD176-CARs mediated T-cell signaling (NF-κB activation) and T-cell activation (CD69, CD137 expression) upon recognition of CD176+ cancer cell lines and unmasked CD176, whereby a short spacer enabled superior target recognition." (PMID 37915564, 2023). "We thus assessed the expression of the early and late T-cell activation markers CD69 and HLA-DR, respectively, as well as that of the proliferation marker KI67 according to PD-1 and CD39 expression in memory Tconv from cancer patients." (PMID 35954341, 2022). "IPS analysis demonstrated the ability of CD69 and SBK1 to predict PD-1/PD-L1 blockade responses in various cancers." (PMID 36045683, 2022). "RT-qPCR and Western blot results showed that the expressions of AGER, CD69, and IL7R in cancer tissues were significantly lower than those in adjacent tissues." (PMID 36358600, 2022). "CD69 and SBK1 are potential predictors of response to cancer immunotherapy using PD-1/PD-L1 blockade." (PMID 36045683, 2022). "In summary, our study indicates that CD69 and SBK1 expression levels can effectively predict cancer response to PD-1/PD-L1 blockade immunotherapy." (PMID 36045683, 2022). "Activated NK cells overexpress CD69, Fas ligand, and TRAIL on their surface, and secrete perforin and granzyme B to kill cancer cells." (PMID 34638944, 2021). "Methylation of ITGAL and ANPEP were down-regulated, while methylation of CD69 and PTPRC were up-regulated in cancer." (PMID 34633989, 2021). "Markers for T and B cell activation (CD69, CD25, 41BB and CD86) and T-cell differentiation (CD45RA-CCR7- effector memory T cells) were elevated in TILs of advanced stage cancers." (PMID 34135436, 2021). "The total frequencies of CD69+CD49a+CD103−CD16−, CD69+CD49a−CD103+CD16−, and CD69+CD49a+CD103+CD16− NK cells detected were independent of clinical parameters, including medication and type of cancer of patients from whom clinical samples were derived." (PMID 31451696, 2019). "FSD13 had a greater ability than wild-type IL-2 in stimulating CD4+ T, CD8+ T, and NK cell proliferation, enhancing the expression of CD69, CD183, CD44, and CD54 in these cells, and triggering cancer cell apoptosis." (PMID 30250191, 2018). "Subsequent co-culture results of the generated CAR-T cells with SKBR3 cancer cell line indicated strong activation in CAR-T cells, which was measured by the high expression of CD69 and CD25." (PMID 28885562, 2017). "A significantly higher proportion of activated CD8 T-cells expressing CD69 and CD107 in early invasive cancer compared to advanced cancer in non inflammatory conditions has been described." (PMID 25595911, 2015). "Interestingly, cell-free PDSs boosted the frequency of CD69+ T cells in both strongly activated CD4+ and CD8+ populations, and the frequencies were even higher in co-cultures with cancer cells." (PMID 40240529, 2025).